MPO (myeloperoxidase)
Diseases named in the same sentence as MPO in open-access papers (continued):
Sharing a sentence is not in itself a finding about the gene and the disease.
periodontitis (continued). "Multiple neutrophil-derived proteolytic enzymes have been shown to be elevated in periodontitis compared to healthy controls, including myeloperoxidase (GCF) and matrix metalloproteinases (e.g., MMP-2 and MMP-9) whose major source in the periodontium is the neutrophil." (PMID 23843954, 2013). "Despite the nonmechanistic nature of the current data, IL-17 has already been shown to present a prominent role in the activation and recruitment of neutrophils to inflammatory sites, and MPO and IL-8 have been reported to be correlated with worse clinical status of periodontitis." (PMID 23304063, 2012). "In a rat periodontitis model, cashew gum polysaccharide (CG‐P)‐containing oral gel significantly reduced alveolar bone loss, decreased the mRNA expression of TNF‐α, IL‐1β, RANKL, and the RANKL/OPG ratio, and lowered myeloperoxidase activity in gingival tissues." (PMID 41476843, 2025). "Therefore, we hypothesize that periodontitis patients with metabolic syndrome will exhibit higher levels of salivary aMMP‐8, tMMP‐8, and MPO compared to systemically healthy patients with periodontitis." (PMID 38852177, 2025). "There are changes in GPX, the ratio of glutathione/oxidized glutathione, and myeloperoxidase (MPO) activity, increases in lipid peroxides, and other indicators in the tissues of periodontitis patients, and GPX elevation may be an antioxidant compensation during oxidative stress." (PMID 36359745, 2022). "This group of inhibitors may include physiological salivary components such as myeloperoxidase (whose concentration increases in periodontitis) and catalase competing for hydrogen peroxide with LPO, or uric acid present in saliva at high concentration and competing with SCN− ions." (PMID 30901933, 2019). "In an acute periodontitis model, this triterpenoid reduced tumor necrosis factor-alpha (TNF-alpha), MPO, and thiobarbituric acid reactive substances (TBARS)." (PMID 40559438, 2025). "The aim of this case–control study is to compare patients with periodontitis and healthy controls regarding the salivary concentrations of extracellular DNA and NET components, including nucleosomes, neutrophil elastase, and myeloperoxidase." (PMID 38256602, 2024). "GCF levels of MPO, beta-glucuronidase (BGD), and NE increase in periodontitis, suggesting that these enzymes are potential markers of periodontal inflammation." (PMID 39554809, 2024). "aMMP-8, MPO, and PMN elastase eventually form a pro-oxidative and proteolytic tissue cascade in stage III/IV-grade b/c periodontitis that can conveniently be identified by the aMMP-8 POCT in 5 min." (PMID 39273368, 2024). "aMMP-8, MPO, and PMN elastase eventually form a proteolytic and pro-oxidative tissue destruction cascade in periodontitis, potentially representing a therapeutic target." (PMID 39273368, 2024). "The effects of anti-infective treatment (scaling and root planning) in 13 periodontitis patients were monitored by aMMP-8, the rate of aMMP-8 RFU activity, tMMP-8, MPO, PMN elastase, TIMP-1, calprotectin, and IL-6 as well as by clinical periodontal parameters." (PMID 39273368, 2024). "In periodontitis-induced inflammation, α- and β-amyrins pretreatment at 5 mg kg−1 significant reduced TNF-alpha, the gingival myeloperoxidase and thiobarbituric acid-reactive substances, retarding acute inflammation in rat model." (PMID 33800018, 2021). "Previous studies have demonstrated that MMP-8, MMP-9, lactoferrin, cystatin C, MPO, PAF, cathepsin B, and ICTP can be used to diagnose periodontitis." (PMID 32503210, 2020). "In spite of the difficulties, this study can be the start of a series of further studies that will confirm or deny the main role of both MMP-9 and MPO in the progression of chronic-inflammatory processes such as DM2 and periodontitis." (PMID 31355267, 2019). "In contrast to periodontitis, PI lesions are more than twice the size and contain a significantly larger area, numbers, and densities of CD138−, CD68−, and MPO-positive cells." (PMID 31817894, 2019).
periodontitis (continued). "MPO levels repeatedly correlate not only with total MMP-8 levels, but also with its active isoenzyme forms; and both MPO and MMP-8 show high accuracy for specific site-diagnosis of chronic periodontitis versus gingivitis and healthy sites." (PMID 28218665, 2017). "In accordance with a previous report, myeloperoxidase, myosin 9, annexin A3, profilin-1, L-plastin (plastin-2/LCP1), S100A8, and S100A9 were detected at higher levels in chronic periodontitis patients compared to healthy individuals." (PMID 21794177, 2011). "This study aimed to evaluate and compare the salivary expression of aMMP‐8, tMMP‐8, and MPO among periodontitis patients with and without metabolic syndrome." (PMID 38852177, 2025). "Our previous findings regarding salivary analytes aMMP8, tMMP-8, and MPO among periodontitis patients with and without MetS-PD and controls demonstrated significant intergroup variation." (PMID 41075005, 2025). "The mean levels of all salivary NETosis biomarkers citH3, ELA, CALPRO, and MPO were elevated in the periodontitis groups (smokers and nonsmokers) than in controls." (PMID 41425261, 2024). "Also, MPO, a pro-oxidative activator of MMP-8, was recorded in this study to be an efficient biomarker of periodontitis." (PMID 39273368, 2024). "Finally, there was a significant difference in the levels of aMMP-8, the rate of MMP-8 activity, tMMP-8, MPO, PMN elastase, and TIMP-1 between the base level of (untreated) patients with periodontitis and 13 periodontally and systemically healthy controls." (PMID 39273368, 2024). "Molecules such as MPO and BGD are proteolytic enzymes released from neutrophil azurophilic granules into the extracellular area following neutrophil stimulation and are promising GCF biomarkers for diagnosing periodontitis." (PMID 39554809, 2024). "aMMP-8, MPO, and PMN elastase may form a proteolytic and pro-oxidative tissue destruction cascade in periodontitis, potentially representing a therapeutic target." (PMID 39273368, 2024). "What’s more, the VNN2 might interact with neutrophil during periodontitis pathogenesis, with positive evidence between VNN2 and neutrophil-related biomarkers, MPO and indicators of β2 integrin-dependent neutrophil adherence and migration." (PMID 36527111, 2022). "To investigate whether oxidative stress played a role in ligature-induced experimental periodontitis and LIPUS protection, we evaluated oxidative stress biomarkers, such as 3-NT, 8-OHdG, and MPO." (PMID 32863960, 2020). "The color from the reaction between salivary MPO and DAB was mainly classified as follows: near colorless in periodontally healthy individuals; moderately brown in gingivitis patients; and intensely brown in periodontitis patients." (PMID 27274868, 2016). "In GCF, results were similar, the highest levels of MPO were also measured in samples derived from PLS patients (median 7.50 ng/μl, range 1.95-13.90 ng/μl), followed by chronic periodontitis patients, aggressive periodontitis, and periodontally healthy controls, respectively." (PMID 25260376, 2014). "In the present study, lower GCF MPO levels in the adjunctive SDD group might suggest that SDD in vivo, and in addition to MMPs, can down-regulate the levels of MPO, a unique neutrophil-derived oxidative up-regulator of MMPs, at the periodontitis sites." (PMID 30669541, 2019). "Salivary MPO activity in gingivitis group was lower than in periodontitis group, but not statistically significant (p = 0.059); the mean difference (0.148) between gingivitis and periodontitis groups was considered as clinically significant value (95% CI = [−0.004]–[0.302])." (PMID 27274868, 2016). "The citH3, ELA, CALPRO, and MPO levels could not differentiate between stage III and IV smokers and nonsmoker periodontitis groups." (PMID 41425261, 2024).
ulcerative colitis (70 papers, 2011 to 2025). An inflammatory bowel disease involving the mucosal surface of the large intestine and rectum. "Measures of myeloperoxidase activity were more closely associated with disease activity in ulcerative colitis patients, with less robust correlations in Crohn’s disease." (PMID 40411448, 2025). "An increase in MPO concentration is associated with ulcerative colitis." (PMID 40717964, 2025). "Neutrophil-myeloperoxidase (MPO), a heme-containing enzyme that generates large amounts of hypochlorous acid during inflammation, contributes to the onset and progression of ulcerative colitis (UC)." (PMID 40699843, 2025). "MPO activity in the MC group was significantly higher compared to the NC group (p < 0.01), confirming the successful establishment of the ulcerative colitis model." (PMID 39697653, 2024). "On the other hand, MPO level were the crucial indicators to evaluate the inflammation function repair of ulcerative colitis." (PMID 38169633, 2024). "In ulcerative colitis, the levels of proinflammatory cytokines, reactive oxygen and nitrogen compounds and the myeloperoxidase (MPO) level, which is an indicator of neutrophil infiltration, are found to be increased." (PMID 39105785, 2024). "In our previous study, patients with inflammatory bowel diseases eligible for biologic therapy had significantly reduced MPO levels in the saliva of patients with ulcerative colitis (UC) compared to patients with Crohn’s disease (CD) and healthy controls." (PMID 37569455, 2023). "Three of them had myeloperoxidase-antineutrophil cytoplasmic antibody-related vasculitis, one immunoglobulin G4-related disease, and one ulcerative colitis." (PMID 36789128, 2023). "MPO is a pro-oxidation and pro-inflammatory enzyme, and its activity is regarded as an important inflammatory indicator of ulcerative colitis." (PMID 35010176, 2021). "As a result of induction therapy, only patients with ulcerative colitis showed a significant increase in salivary IgA and myeloperoxidase to levels comparable to the controls." (PMID 34947940, 2021). "In TNBS-induced ulcerative colitis, UC rats are represented by diarrhea, ulceration of colon tissue, and enhancement of MPO activity in serum." (PMID 34630607, 2021). "Experimental studies demonstrated that AAL improved trinitro-benzene-sulfonic acid (TNBX)-induced ulcerative colitis in rats by inhibiting inflammatory cell infiltrates, and decreasing the MPO activity and frequency of diarrhea." (PMID 33776618, 2021). "It has been documented that the inhibition of this enzyme by the anti-diabetic drug acarbose induces H2, which causes reductions in the levels of oxidative stress markers, such as MPO, thus improving the symptoms in ulcerative colitis." (PMID 33441125, 2021). "Hesperidin, a component of Pericarpium Citri reticulatae, can ameliorate dextran sulfate sodium-induced ulcerative colitis in mice and reduce the amount of mucosal damage, myeloperoxidase, malondialdehyde activities, and serum IL-6 levels." (PMID 33817258, 2020). "Studies have shown that MPO activity increases gradually with the increase of inflammation degree in rat model of ulcerative colitis induced by acetic acid." (PMID 31139644, 2019). "In vivo, BRP has been seen to promote protective effects against ulcerative colitis in a rat model, reducing gross and histological inflammatory lesions and decreasing the levels of myeloperoxidase and iNOS in colon tissue." (PMID 29390009, 2018). "Increased MPO activity is often correlated with ulcerative colitis (UC), a form of IBD and patients with IBD are at a higher risk of colon cancer." (PMID 24040197, 2013). "In line with reports on the rise of MPO activity during the active phase of the disease in patients who have ulcerative colitis and Crohn’s disease, as well as in various animal models of IBDs, we recorded the rise in MPO activity in all mice subjected to the induction of experimental colitis." (PMID 40305159, 2025).
ulcerative colitis (continued). "Furthermore, consistent with in vitro findings, both probiotics and paraprobiotics effectively improved histological scores and reduced myeloperoxidase levels in a DSS-induced ulcerative colitis mouse model." (PMID 40016142, 2025). "Furthermore, consistent with in vitro findings, both probiotics and paraprobiotics were effective in improving histological scores and reducing MPO levels in a DSS-induced ulcerative colitis mouse model." (PMID 40016142, 2025). "Oral administration of C. bovis was also found to alleviate the inflammatory damage in the colon tissue of mice ulcerative colitis model induced by dextran sulfate sodium, accompanied by reduced levels of myeloperoxidase, SOD, and mRNA expression of IL-1β, IL-6, and TNF-α." (PMID 36903252, 2023). "Neutrophil-myeloperoxidase (MPO) is an abundant enzyme that catalyzes the production of reactive oxygen species and are biomarkers of oxidative damage that is increased in the intestinal mucosa of patients with ulcerative colitis." (PMID 37815528, 2023). "In addition to a reduction in TNF-R1 and MPO, salivary levels of immunoglobulin A were also found to be significantly reduced in both Crohn’s disease and ulcerative colitis patients relative to the controls." (PMID 34575091, 2021). "XO, an enzyme present in the intestinal mucosa, is an important source of ROS and is involved in injuries to the gastrointestinal tract, whereas the activity of MPO in inflamed intestinal mucosa in patients with ulcerative colitis (UC) contributes to the progression of malignant tumors." (PMID 33918143, 2021). "Consistent with MPO potentially playing a role in the pathogenesis of IBD, inflamed mouse colon and colon specimens from patients with both ulcerative colitis (UC) and Crohn’s disease (CD) show higher 3-Cl-Tyr and MPO levels than corresponding healthy control tissue." (PMID 33041796, 2020). "MfB beverage showed significant reduction of symptoms associated to ulcerative colitis and improved the colon shortening and mucosal colonic damage, but it was not able to reduce the increase of myeloperoxidase levels produced by DSS." (PMID 30987294, 2019). "MPO is a well-established biomarker of inflammation in various conditions such as multiple sclerosis, ischaemic heart disease and acute coronary syndromes, as well as ulcerative colitis." (PMID 29894476, 2018). "In a mouse model of ulcerative colitis, ARB displayed marked competence in mitigating intestinal pathological findings through the suppression of myeloperoxidase and pro-inflammatory cytokines." (PMID 39065759, 2024). "In ulcerative colitis models, ALO reduces LTB4 and TNF‐α levels and inhibits myeloperoxidase activity and TNF‐α and IL‐1β mRNA expression." (PMID 38888378, 2024). "In a mouse model of ulcerative colitis, ARB suppressed myeloperoxidase activity, leading to improved intestinal pathology." (PMID 39065759, 2024). "SA also effectively ameliorated ulcerative colitis in rats by suppressing TNF-α, interleukin 6 (IL-6), Myeloperoxidase (MPO), Prostaglandin E2 (PGE2), cyclooxygenase-2 (COX-2), and NF-κB." (PMID 37444374, 2023). "Neutrophils and macrophages were immunostained using the markers myeloperoxidase (MPO) and F4/80, respectively, to examine the impact of FTB on inflammation-related cell accumulation in the colon of a DSS-induced ulcerative colitis mouse model." (PMID 37375714, 2023). "Decreases IL-1β, TNF-α, MDA, MPO, NF-κB p65, TRAF6, LC3, Beclin1, p62 levels and cell apoptosis; increases SOD activity; and exerts obvious therapeutic effect on rat ulcerative colitis." (PMID 35566359, 2022). "The administration of PO reversed the colonic damage and reduced the disease activity indicators, including levels of colonic myeloperoxidase (MPO) in the 2,4,6-trinitrobenzenesulfonic acid-induced model of ulcerative colitis in rats." (PMID 33413544, 2021).
ulcerative colitis (continued). "To further verify the effect of the free polyphenol extract of cherry on ulcerative colitis in mice, we measured the activity of enzymes (ALT, CAT, GSH-Px, SOD), and the levels of inflammatory cytokines (MDA, MPO, NO)." (PMID 35010176, 2021). "The administration of SASP or the polyphenol extract significantly decreased the activity of MPO (p < 0.05), suggesting their potential protective effects on DSS-induced ulcerative colitis in vivo." (PMID 35010176, 2021). "The activity of colonic MPO of C mice was about 2.5-fold higher than that of N mice, demonstrating that DSS treatment induced serious ulcerative colitis." (PMID 35010176, 2021). "It has been demonstrated that colonic tissue levels of MPO and MCP-1 were increased in ulcerative colitis." (PMID 33995942, 2021). "In trinitrobenzenesulfonic acid (TNBS)-induced ulcerative colitis (UC) model, ST36 EA decreased the concentration of TNF-α in serum and MPO activities, and TNF-α mRNA expression in the colon." (PMID 35095910, 2021). "UroA/UAS03 treatment also reduced neutrophil infiltration as evident from myeloperoxidase (MPO) activity as well as serum inflammatory markers such as IL-6, TNF-α, CXCL1, and IL-1β that are hallmarks of ulcerative colitis." (PMID 30626868, 2019). "Our findings indicate that SPS can lower the expression levels of IgG and IgM while downregulating MPO expression, suggesting that SPS may mediate immune regulation to alleviate ulcerative colitis." (PMID 41008172, 2025). "Therefore, PWE can enhance the activities of GSH and SOD in DSS-induced ulcerative colitis mice, and reduce the contents of NO, MDA, and MPO in colon tissue." (PMID 35630568, 2022). "Furthermore, another coumarin—osthol relieved the symptoms of ulcerative colitis by reduction of TNF-α level and decrease in the activity of MPO." (PMID 33579030, 2021). "The MPO activity of the SFN group was significantly lower than that of the DSS group (P < 0.05), which indirectly proved that SFN reduced the inflammatory degree of acute ulcerative colitis in mice." (PMID 32621086, 2020). "MPO activity, which is an indicator of neutrophil infiltration, was shown to increase with the severity of inflammatory damage as observed by microscopic analysis in many studies where DSS was used to induce ulcerative colitis in mice." (PMID 31999939, 2020). "Allicin can regulate CD68, MPO, MDA, and inflammation factor expression to attenuate DSS-induced ulcerative colitis, and its mechanism may be related to the regulation of signal transducer and activator of transcription 3 (STAT3) and nuclear factor-κB (NF-κB) signaling pathway activity." (PMID 31139644, 2019).